EGFR (epidermal growth factor receptor)
Diseases named in the same sentence as EGFR in open-access papers (continued):
Sharing a sentence is not in itself a finding about the gene and the disease.
colorectal cancer (continued). "A previous study has demonstrated that the methylations on the EGFR extracellular domain mediated by PRMT1 enhance receptor function in colorectal cancer cells, affecting the EGF-EGFR binding affinity to promote tumorigenesis." (PMID 40612681, 2025). "These hybrids function as dual inhibitors of epidermal growth factor receptor (EGFR) and cyclooxygenase-2 (COX-2), two key targets implicated in colorectal cancer proliferation and inflammation." (PMID 41149466, 2025). "In light of these findings, the most effective first-line regimen for wild-type RAS, left-sided colorectal cancer is doublet chemotherapy (FOLFOX or FOLFIRI) combined with an anti-EGFR antibody." (PMID 39941797, 2025). "In this assay, we used the FDA-approved anti-EGFR mAb, cetuximab, in combination with EGFR-overexpressing colorectal cancer cell lines HCT116 and HT29." (PMID 40136470, 2025). "Characteristics and findings in principal clinical trials carried out with ICIs or bevacizumab or anti‐EGFR mAbs as first line therapy in advanced colorectal cancer (aCRC)." (PMID 41020040, 2025). "KRAS inhibitors (e.g., sotorasib and adagrasib) in combination with the EGFR antibody have been proved more effective than either agent alone in patients with colorectal cancer." (PMID 40304209, 2025). "The epidermal growth factor receptor (EGFR) is a validated therapeutic target for RAS/RAF wild‐type colorectal cancer (CRC)." (PMID 39560161, 2025). "The EGFR (epidermal growth factor receptor) pathway in colorectal cancer (CRC) is a crucial signaling cascade that plays a central role in tumor growth and progression." (PMID 39941081, 2025). "The presence of the targeting peptide allowed for enhanced binding and internalization in EGFR-overexpressing colorectal cancer cells (SW480), through a receptor-specific internalization pathway." (PMID 39940134, 2025). "Immune checkpoint inhibition (PD-1 ± CTLA-4) with anti-EGFR demonstrated activity in previously treated colorectal cancer in two prior studies, with ORR 8% to 35% and median PFS 3.6 to 5.7 months." (PMID 41171165, 2025). "Studies have demonstrated that PRNP modulates the expression of MAPK and FOXO3a via the epidermal growth factor receptor signaling pathway, influencing the emergence of platinum resistance in colorectal cancer." (PMID 41394830, 2025). "FMRP protein also played a significant role in the progression of colorectal cancer by stabilizing the mRNA of epidermal growth factor receptor (EGFR), thereby enhancing cellular proliferation and migration." (PMID 40271197, 2025). "Prior studies have shown that PL’s novel proteoglycan (P1) inhibits colorectal cancer by boosting the immune response to T cells and IgA, and by disrupting the Reg IV/EGFR/Akt signaling pathway." (PMID 40002150, 2025). "In colorectal cancer, CB-839 synergizes with the EGFR inhibitor cetuximab to decrease cell growth in vitro and tumor development in vivo." (PMID 40943167, 2025). "Previous studies have investigated cfDNA BRAFV600E as a biomarker in colorectal cancer and its role in predicting resistance to anti-EGFR therapy." (PMID 40149427, 2025). "Among the various molecular mechanisms of chemotherapy resistance in colorectal cancer, the dysregulation of key signaling pathways, such as EGFR, PI3K, and mTOR, plays a prominent role." (PMID 39941081, 2025). "The results evaluation revealed that P1 can directly suppress colorectal cancer by disrupting the signaling pathway involving Reg IV/EGFR/Akt." (PMID 40002150, 2025). "While small molecule inhibitors targeting the intracellular EGFR TK domain have demonstrated activity in other malignancies, only antibodies directed at the ligand-binding domain have shown efficacy in colorectal cancer." (PMID 40722718, 2025). "In colorectal cancer, clinical benefit requires the addition of EGFR inhibitors to overcome pathway reactivation." (PMID 40332392, 2025).
colorectal cancer (continued). "The development of anti‐epidermal growth factor receptor treatment in colorectal cancer is a paradigm of how the understanding of molecular mechanisms can rapidly inform and refine the clinical use of anticancer agents." (PMID 39470386, 2025). "These fusion proteins were analyzed for cell binding and cell death induction using the EGFR-expressing colorectal cancer cell lines Colo205 and HCT116." (PMID 40328809, 2025). "While RHBDD1 promotes colorectal cancer (CRC) via TGFα/EGFR/ERK signaling, our study reveals a distinct mechanism in ESCC, where RHBDD1 enhances invasion by activating Wnt/β-catenin via ELK3." (PMID 40787199, 2025). "In colorectal cancer, targeted therapies (such as EGFR-targeted antibody therapy) and immune therapies (such as PD-1 inhibitors) have become widely used." (PMID 41269529, 2025). "Taken together, we conclude that our anti-SIRPα mAbs effectively block the SIRPα-CD47 interaction, thereby enhancing the phagocytic activity induced by the anti-EGFR mAb on colorectal cancer cells." (PMID 40136470, 2025). "In Phase II trials of cetuximab treatment in patients with epidermal growth factor receptor (EGFR) positive refractory colorectal cancer, more than 86% of patients developed acne-like skin rash, including 18% developing grade 3 symptoms." (PMID 41246356, 2025). "KEGG pathway enrichment analysis identified 141 significantly associated pathways (p < 0.05), including VEGF signaling, EGFR tyrosine kinase inhibitor resistance, estrogen signaling, PI3K–Akt signaling, and pathways related to colorectal cancer." (PMID 40283891, 2025). "Previous research has shown that lidocaine has antiproliferative effects on colorectal cancer cells (SW480 and HCT116), causing cell death by suppressing the EGFR through the upregulation of miR-520a-3p, which targets EGFR." (PMID 41226554, 2025). "Consistently, combining glecirasib with cetuximab, an EGFR antibody, enhanced antitumor efficiency against colorectal cancer in preclinical models." (PMID 40304209, 2025). "The combination of cetuximab (an EGFR inhibitor) and encorafenib (a BRAF inhibitor) has been approved for treating BRAF-mutated colorectal cancer in the U.S. and Europe." (PMID 39757310, 2025). "The NIR-based quantitative imaging tool for EGFR-positive colorectal cancer detection has been extensively studied." (PMID 40906195, 2025). "Functionally, HSP90 acts as a central molecular chaperone that stabilizes multiple oncogenic proteins, including EGFR, thereby promoting sustained signaling, stress tolerance, and therapeutic resistance in colorectal cancer." (PMID 41319168, 2025). "Apc mutation is accompanied by increased EGFR expression and activity in the tumors, which explains the efficacy of EGFR-targeting therapeutics in the treatment of colorectal cancer patients of specific molecular subtypes." (PMID 40005135, 2025). "Comparison of the sensitivities of the four groups of colorectal cancer cell lines to representative porcupine inhibitors, tankyrase inhibitors, and EGFR inhibitors was performed using data from the GDSC project." (PMID 40061138, 2025). "Chemotherapy combined with anti-EGFR or anti-VEGF agents has become the standard of care for advanced colorectal cancer, guided by molecular profiling and the anatomical characteristics of tumours." (PMID 41355781, 2025). "Within the colorectal cancer (COAD) dataset, the epidermal growth factor receptor (EGFR) gene harbors a specific missense mutation, G465E, which is localized in the extracellular domain of the protein." (PMID 41142752, 2025). "In this study, the imaging characteristics of cetuximab-IRDye800CW were systematically validated in two well-established EGFR-overexpressing colorectal cancer cell lines (LS174T and SW948) as well as in an EGFR-high PDX model." (PMID 41346398, 2025).
colorectal cancer (continued). "In comparison with non-targeted PMNPs, GE11-conjugated nanocarriers showed a significantly higher internalization into EGFR-overexpressing colorectal cancer cells HCT116 and higher tumor uptake 24 h post-injection." (PMID 39940134, 2025). "EGFR expression is also common in colorectal cancer cells (CRC) and we identified two human CRC cell lines that had contrasting patterns of expression: EGFRhigh HCT116 and EGFRintermediate RKO." (PMID 41219228, 2025). "In conclusion, our case indicates a strong relationship between black pigmentation on the tongue and the long-term use of minocycline for the treatment of EGFR inhibitor-induced skin lesions in a colorectal cancer patient." (PMID 40130130, 2025). "This is consistent with previous studies reporting apoptosis induction by 3BP in colorectal cancer models resistant to EGFR inhibitors." (PMID 40563683, 2025). "This relationship likely stems from impaired renal tubular magnesium reabsorption induced by EGFR inhibition, a mechanism validated in colorectal cancer cohorts,although its relevance in HNC remains unresolved." (PMID 41235256, 2025). "Another example is cetuximab, which targets the epidermal growth factor receptor (EGFR) overexpressed in colorectal cancer cells." (PMID 41267750, 2025). "Collectively, these findings highlight the pivotal role of USP11 in promoting EGFR-driven colorectal cancer progression." (PMID 41419456, 2025). "The panel reviewed over 4000 scientific publications and determined that genetic alterations within the EGFR signaling pathway are predictive of resistance to EGFR-targeted treatments in colorectal cancer patients." (PMID 40724602, 2025). "The binding of the different fusion proteins to the EGFR-expressing human colorectal cancer cell lines Colo205 and HCT116 were investigated by flow cytometry." (PMID 40328809, 2025). "This was motivated by the low response rates of human EOC to ICIs (<10%) and the reported ability of high AREG levels to predict response of colorectal cancer patients to anti-EGFR antibodies." (PMID 40666944, 2025). "EGFR-mediated signaling was identified as the dominant mechanism of resistance to KRASG12C inhibitors in colorectal cancer." (PMID 40141164, 2025). "In colorectal cancer, epidermal growth factor receptor (EGFR) inhibitors like cetuximab and panitumumab are prescribed in RAS wild-type tumours, whereas angiogenesis is suppressed using VEGF inhibitors such as bevacizumab." (PMID 40650758, 2025). "Their respective IC50 values against HT-29 colorectal cancer cells were 0.9 μM (C4 for EGFR) and 0.5 μM (G4 for COX-2), indicating strong potency and selectivity." (PMID 41149466, 2025). "In colorectal carcinoma models, Probody-engineered EGFR/CD3 bispecific antibodies (e.g., CI107) demonstrated a marked reduction in toxicity while maintaining therapeutic efficacy." (PMID 41333481, 2025). "Although the overall prevalence of MET amplifications in colorectal carcinoma is low (0.46%), it is enriched in ctDNA of patients with anti-EGFR refractory disease." (PMID 41590338, 2025). "We also tested two lines with distinct drug sensitivities based on alternative genomic contexts (one BRAF mutant melanoma (A375) sensitive to RAF inhibition and one KRAS wild type colorectal cancer (LIM1215) sensitive to EGFR inhibition)." (PMID 38822082, 2024). "In fact, vemurafenib, dabrafenib, or encorafenib do render benefits to colorectal cancer patients, however their use needs to be supplemented by simultaneous administration of anti-EGFR antibodies to avoid feedback activation of the EGFR." (PMID 38612902, 2024). "Colorectal cancer (CRC) often necessitates cetuximab (an EGFR-targeting monoclonal antibody) for treatment." (PMID 38724565, 2024).
colorectal cancer (continued). "In another study, conjugation of NDs with paclitaxel, a microtubule inhibitor, and cetuximab, a specific monoclonal antibody against epidermal growth factor receptor (EGFR), enhanced the mitotic catastrophe and apoptosis induction of colorectal cancer cells." (PMID 39474040, 2024). "The first targeted therapeutic agent approved by the Food and Drug Administration (FDA) for colorectal cancer was cetuximab, a monoclonal antibody designed to target EGFR." (PMID 38542291, 2024). "Rationale: the proto-oncogene KRAS is frequently mutated in colorectal cancer (CRC), leading to inherent resistance against monoclonal antibodies targeting the epidermal growth factor receptor (EGFR), such as cetuximab." (PMID 39310106, 2024). "As an example, IGF2BP3, an RNA‐binding protein, improves the steadiness and translation of EGFR mRNA, thereby boosting colorectal cancer cells' resistance to cetuximab, an EGFR‐targeting antibody." (PMID 38717936, 2024). "PEPD is a peptidase that has been shown to inhibit tumor signaling in colorectal cancer through promoting epidermal growth factor receptor inhibition." (PMID 38732562, 2024). "Through these diverse downstream signaling pathways, EGFR plays an important role in the carcinogenesis of colorectal cancers." (PMID 38542291, 2024). "The epidermal growth factor receptor (EGFR) is an RTK whose overexpression has been implicated in many solid cancers, including HNSCC, lung, pancreas, and colorectal cancers." (PMID 39457986, 2024). "We provide evidence that in human colorectal cancer cells with a hyperactive WNT pathway due to APC mutations, knockout of RNF43 promotes cancer cell growth by activating EGFR signaling." (PMID 38260423, 2024). "In colorectal cancer, cetuximab, which is a chimeric antibody against the epidermal growth factor receptor (EGFR), is effective only against wild-type rat sarcoma (RAS) family oncogenes." (PMID 38549846, 2024). "In this regard, we have decorated the protruding (P) domain of MrN-VLP with GE11 peptide to enhance specific binding and internalization towards epidermal growth factor receptor (EGFR) positive colorectal cancer cells, SW480." (PMID 38459500, 2024). "Dysregulation of the EGF receptor (EGFR) signaling pathway is a typical observation in malignancies, especially colorectal cancer (CRC)." (PMID 39590368, 2024). "PAN is an anti-HER1/EGFR monoclonal antibody approved by the FDA for the treatment of HER1-expressing colorectal cancers and was used as the model antibody for this study." (PMID 38675440, 2024). "In contrast, targeting EGFR in BRAF-mutant colorectal cancer has been successful, underscoring the significance and possibility of a variety of context-dependent mechanisms of MAPK reactivation." (PMID 39001489, 2024). "Is rechallenge with anti–epidermal growth factor receptor (EGFR) inhibitors a therapeutic option in patients with refractory circulating tumor DNA (ctDNA) RAS/BRAF wild-type (wt) colorectal cancer (CRC)?" (PMID 38592721, 2024). "EGFR gene amplification and heterogenous expression was observed between CTCs from the same patient with colorectal cancer." (PMID 38398206, 2024). "Adaptive mutagenesis observed in colorectal cancer (CRC) cells upon exposure to EGFR inhibitors contributes to the development of resistance and recurrence." (PMID 39102671, 2024). "Squamous cell carcinoma of the head and neck region shares a high EGFR expression signature with carcinomas of other regions, such as colorectal cancer." (PMID 38943031, 2024). "aimed to investigate the link between methylglyoxal (MGO), a by-product of glycolysis, and resistance to cetuximab anti-epidermal growth factor receptor (anti-EGFR) antibodies in colorectal cancer." (PMID 39301314, 2024). "In a phase 1b study, the safety and pharmacokinetics (PK) of combining regorafenib with cetuximab (an EGFR inhibitor) were assessed in patients with advanced refractory solid tumors, including gastrointestinal stromal tumors, colorectal cancer, and HCC." (PMID 38816668, 2024).
colorectal cancer (continued). "Anti-EGFR monoclonal antibodies, when combined with chemotherapy, demonstrate a synergistic effect in advanced colorectal cancer and are part of the standard treatment regimen." (PMID 39123483, 2024). "Treatment switching was included in the protocol for Study 20020408 based on prior evidence of the activity of panitumumab and cetuximab, a similar anti-EGFR (epidermal growth factor receptor) monoclonal antibody, in colorectal cancer." (PMID 38253996, 2024). "During the FIRE-6 study, colorectal cancer patients were treated with the anti-EGFR antibody cetuximab alone or in combination with the anti-PDL1 antibody avelumab." (PMID 39791733, 2024). "In the last decade, preclinical and translational models have identified two main strategies for colorectal cancer cells to evade EGFR inhibition: reactivation of the MAPK pathway and mutations in the extracellular domain of EGFR (EGFR ECD)." (PMID 38711991, 2024). "Research has shown that EGFR is involved in signal pathway dysregulation in cancer cells, typically occurring in colorectal cancer cells." (PMID 39682940, 2024). "The RAS gene is also an important target for colorectal cancer treatment, and KRAS mutation status can predict the therapeutic effect of anti‐epidermal growth factor (EGFR)." (PMID 38698687, 2024). "Meanwhile, a phase 1 study was launched to test the efficacy of combining sotorasib with the EGFR inhibitor panitumumab in treating chemotherapy-resistant colorectal cancer, which confirmed its safety and efficacy (NCT04185883)." (PMID 38816668, 2024). "Despite the introduction of new molecular classifications, advanced colorectal cancer (CRC) is treated with chemotherapy supplemented with anti-EGFR and anti-VEGF targeted therapy." (PMID 38409377, 2024). "With respect to RAC1B, in vitro and in vivo experiments revealed that RAC1B deletion in colorectal cancer decreased EGFR phosphorylation and downstream pathway activation, suggesting RAC1B plays a significant role in EGFR signaling." (PMID 39001533, 2024). "The activation of PI3K/AKT as an escape mechanism to vertical suppression of the EGFR/RAS/MAPK pathway by EGFR and MEK inhibitors in KRAS-mutant colorectal cancer has also been reported and is linked to drug resistance and disease recurrence." (PMID 38409090, 2024). "Anti-EGFR monoclonal antibodies like cetuximab and panitumumab have been developed to target EGFR in colorectal cancer, particularly in patients with wild-type RAS status." (PMID 39130636, 2024). "For instance, MSC-derived exosomes have been reported to decrease the mRNA levels of Aquaporin-5 and EGFR in colorectal cancer cells, both of which are important signaling molecules regulating tumor proliferation and metastasis." (PMID 38612457, 2024). "In colorectal cancer, mutations in PIK3CA are associated with resistance to therapy by anti-EGFR monoclonal antibodies." (PMID 39768623, 2024). "HB-EGF binds to the EGF receptor (EGFR)/ErbB1, promoting colorectal cancer (CRC) cell survival and proliferation and the progression of colonic adenocarcinoma." (PMID 39419989, 2024). "This analysis of the C-CAT database demonstrates that rare RAS variants, detectable only through comprehensive genomic profiling, are associated with significantly poorer outcomes in patients receiving anti-EGFR therapy for colorectal cancer." (PMID 39727997, 2024). "We previously demonstrated the therapeutic efficacy of encorafenib (BRAF inhibitor) in combination with the epidermal growth factor receptor (EGFR) inhibitor cetuximab for the treatment of patients with advanced colorectal cancer." (PMID 39018564, 2024). "Subsequently, we investigated the impact of depleting ZNRF3 or RNF43 on EGFR clearance at the cell surface in mouse embryonic fibroblasts (MEFs) and human cancer cell lines including APC-mutated colorectal cancer cells." (PMID 38260423, 2024).